HOTAIR (HOX transcript antisense RNA)
Diseases named in the same sentence as HOTAIR in open-access papers (continued):
Sharing a sentence is not in itself a finding about the gene and the disease.
tumor (continued). "In this study we have analyzed the expression of HOTAIR on our GEP-NEN cases, highlighting its gradual upregulation from the NETG1 to the more prognostically unfavorable NECG3 tumor type." (PMID 34208964, 2021). "LncRNA H19, HOTAIR, and MVIH mainly regulate the proliferation, migration, invasion and angiogenesis of tumor cells by regulating VEGF, VASH2, and miR138/HIF1α axis." (PMID 34616746, 2021). "The disruption of the HOTAIR/miR-20a-5p/HMGA2 axis alleviates tumor growth and shrinks tumor volume in vivo." (PMID 34073224, 2021). "For example, some researchers have found that HOTAIR, a long non-coding RNA, was significantly increased in LSCC and is closely related to tumor progression, as well as the occurrence, metastasis, and poor prognosis of tumors." (PMID 34198263, 2021). "FOXC1 binding to the upstream region of HOTAIR, induces its overexpression, and in turn, HOTAIR is able to negatively regulate the expression of miRga-1, promoting HCC cell proliferation and progression in tumor xenografts." (PMID 33540611, 2021). "Our final panel consisted of seven up‐regulated DElncRNAs (CCAT1, CCAT2, H19, HOTAIR, HULC, MALAT1, PCAT1), which were also known as oncolncRNAs and three down‐regulated lncRNAs (MEG3, PTENP1, and TUSC7) as tumor suppressor lncRNAs (tslncRNAs)." (PMID 33094859, 2021). "Down-regulation of HOTAIR improves sensitivity of these malignant cells to the indicated chemical agents, through up-regulating HOXA1 expression, leading to tumour growth contraction as well as induction of cell cycle arrest and apoptosis." (PMID 32245498, 2020). "This specifically impairs HOTAIR/EZH2 interaction, thereby inhibiting the H3K27-mediated trimethylation of NLK, the target of HOTAIR, and consequently diminishing tumor metastasis through the Wnt/β-catenin pathway." (PMID 32635388, 2020). "LncRNAs can function either as oncogenes (e.g., HOTAIR, MALAT1, H19) or as tumor suppressors (e.g., HOTAIRM1, NKILA, XIST) by targeting genes that foster or prevent tumor development and progression, respectively." (PMID 33049922, 2020). "Some lncRNAs were found to be widely dysregulated, such as HOTAIR (HOX transcript antisense RNA), whereas others are specifically altered in one or a few tumor types." (PMID 32967233, 2020). "For instance, H19, HOTAIR, MALAT1, TUG1, GAS5, and CCAT1, were found to play important roles in tumor initiation and development 44-49." (PMID 32922554, 2020). "Results showed that genistein inhibited PCa cell growth through upregulation of tumor suppressor miR-34a, which directly targets HOX Transcript Antisense RNA (HOTAIR), a lncRNA that regulates key pathways in PCa invasion and metastasis." (PMID 32268584, 2020). "Furthermore, interference of HOTAIR could attenuate BC tumor growth in vivo." (PMID 32694942, 2020). "HOTAIR forms a repressor complex through interaction with PRC2 and LSD1 that leads in tumor invasion." (PMID 31956395, 2020). "Collectively, these results indicated that HOTAIR mediated the expression of HK2, which contributes to tumour growth and chemosensitivity in vivo." (PMID 32279420, 2020). "HOTAIR can bind to RUNX3 protein, which functions as a tumor suppressor in multiple malignancies, and promote the interaction between RUNX3 and the E3 ubiquitin ligase MEX3B, inducing degradation via MEX3B-mediated ubiquitination." (PMID 32928281, 2020). "In OSCC tissues, HOTAIR (HOX transcription antisense RNA) was highly expressed, and its expression level was correlated with tumor size, TNM (Tumor Node Metastasis) stage, and prognosis of OSCC." (PMID 31133028, 2019). "LncRNAs known to be a regulatory factor of tumor stem cells included GAS5, NEAT1, SOX2OT, Malat-1, HOTAIR, PVT1, BCAR4 and RBM5-AS1." (PMID 31143372, 2019). "Despite the strong correlation between HOTAIR expression, EMT, and tumor progression, studies on the molecular events regulating the transcription of this lncRNA are still limited." (PMID 30154449, 2019).
tumor (continued). "Actually, numerous lncRNAs function as oncogenes or tumor-suppressor genes, which were reported to be involved in metastasis and prognosis of HCC, such as MEG3, GAS5, HOTAIR, HULC, H19, and MALAT1." (PMID 31500187, 2019). "By binding to the specific 36G46A micro-domain of HOTAIR, ADQ efficiently abrogate the HOTAIR/EZH2 interaction, thereby inhibiting H3K27-mediated tri-methylation of the NLK and consequently inhibiting tumor metastasis." (PMID 30764859, 2019). "In order to study the effects of HOTAIR and HOXA5 on HL-60 cells in vivo, we established xenograft tumor model in nude mice." (PMID 31168296, 2019). "More importantly, suppression of HOTAIR in HCC cells sensitizes them to chemotherapeutic treatments such as doxorubicin and cisplatin, suggesting HOTAIR to be a biomarker of HCC tumor recurrence." (PMID 31056726, 2019). "Depletion of HOTAIR has also been shown to reduce HCC proliferation, suggesting its role in promoting tumor cell growth." (PMID 31056726, 2019). "Our study demonstrated a novel function of lncRNA HOTAIR in promoting exosome secretion from HCC cells and provided a new understanding of lncRNAs in tumor cell biology." (PMID 30943982, 2019). "More specifically, 4 lncRNAs (CCAT1, CCAT2, HOTAIR, and UCA1) were upregulated, while 2 lncRNAs (MALAT1 and TUG1) and 1 circRNA (CDR1AS) were downregulated in CRC tumor tissues compared to NATs." (PMID 30195762, 2018). "In SOC, Knockdown of HOTAIR inhibited A2780 and OVCA429 cells proliferation in vitro and impaired tumor growth in vivo." (PMID 29921308, 2018). "HOTAIR levels were positively correlated with the FIGO stage, histological grade of the tumor, lymph node metastasis." (PMID 29921308, 2018). "Knockdown of CCAT2, FOXCUT, HOTAIR, TUG1 and UCA1 can suppress various aspects of tumor progression." (PMID 29416703, 2018). "We compared the expression levels of nine hypoxia-related lncRNAs39, 40, 41 (H19, HOTAIR, NEAT1, linc-ROR, UCA1, WT1, HINCUT1, LINK-A, LincRNA-p21) between tumor central and peripheral cells." (PMID 29106390, 2018). "Knockdown or depletion of HOTAIR, LOC100507661, NEAT1 as well as overexpression of NAMA can inhibit tumor progression." (PMID 29416703, 2018). "Radiotherapy reduced the expression of HOTAIR and HIF-1α in tumor tissues and HeLa cells or C33A cells." (PMID 30355300, 2018). "In an investigation of HOTAIR, forkhead box C1 (FOXC1), and miR-1, levels of HOTAIR and FOXC1 were increased, while levels of miR-1 were decreased in HCC tissues and HepG2 cells compared to normal liver cells and adjacent non-tumor tissues." (PMID 30159431, 2017). "For example, lncRNA BANCR functions as a tumor suppressor in NSCLC, whereas HOTAIR and MALAT1 promote oncogenic functions in NSCLC." (PMID 29228680, 2017). "Briefly, the present study suggests that glycolysis is involved in HOTAIR/miR-125- and miR-143/HK2-mediated tumour activation." (PMID 29156804, 2017). "We also highlighted common long non-coding RNA molecules such as HULC, HOTAIR, MALAT1, XIST, H19 and GAS5, which mediate the two-way interactions between stroma and tumor." (PMID 28392501, 2017). "Suppressing HOTAIR upregulates the HOXA5 level and downregulates MMP2 and MMP9, which are critical players in tumor invasion and metastasis." (PMID 28931862, 2017). "We analyzed HOTAIR transcripts by transcript per million (TPM) and percentage of each isoform in the tumor samples using RSEM." (PMID 28846832, 2017). "Reduction of HOTAIR expression results in a decrease in HEC-1A endometrial cancer cell tumorgenicity and decreases tumor sizes in an in vivo model of xenografted HEC-1A cells." (PMID 28637507, 2017). "Overexpression of HOTAIR in the immunodeficient nude mouse model (nu/nu) resulted in enhanced HCC cell proliferation and progression of tumor xenografts." (PMID 30159431, 2017).
tumor (continued). "This study firstly demonstrated that miR-193a acted as tumor suppressor in CRPC and the autoregulatory feedback loop of HOTAIR/EZH2/miR-193a served an important mechanism in PCa development." (PMID 29141691, 2017). "Some exhibit hallmarks of tumor suppression, such as MEG3, while others, such as HOTAIR, behave as oncogenes through increased proliferation and reduced survival." (PMID 29113413, 2017). "We found HOTAIR and HOTAIRM1 were differently expressed between tumor and normal breast tissue based on our criteria." (PMID 27597120, 2016). "The mechanisms of HOTAIR regulating the initiation and progression of CRC include relying on Polycomb Repressive Complex (PRC) complex to silence tumor suppressor genes and being involved in EMT process." (PMID 27143813, 2016). "lncRNAs involved in the regulation of tumor metastasis have also been reported, and include MALAT-1 and HOX antisense intergenic RNA (HOTAIR)." (PMID 27154193, 2016). "Among them, HOTAIR, AFAP1-AS1, POU3F3, HNF1A-AS1, PlncRNA1, SPRY4-IT1, ENST00000435885.1 and ENST00000547963.1 were significantly higher in most of ESCC tumor tissues compared with paired adjacent normal tissues." (PMID 25608466, 2015). "A recent study demonstrated that increased HOTAIR expression, as assessed by qPCR in CRC tissues, positively correlates with advanced tumor stage, high recurrence rate, and short metastasis-free and OS intervals of the patients." (PMID 26064090, 2015). "While there is an increasing interest in lncRNAs, to date only a handful has been investigated in HCC, including highly up-regulated in HCC, such as HULC, HOTAIR, H19, HEIH and MVIH, and down-regulated in tumor tissues, such as MEG3, hDreh and LET." (PMID 26674525, 2015). "HOTAIR, a ~2.2-kb long non-coding RNA transcribed from the HOXC locus, is over-expressed in most solid cancers and is correlated with the tumor invasion, progression, metastasis and poor prognosis." (PMID 26183397, 2015). "Among them, HOTAIR, PVT1, H19, MALAT1, GHET1 and HULC were significantly higher in tumor tissues compared with control tissues." (PMID 26096073, 2015). "The results demonstrated that the HOTAIR expression in clinical EOC tissues and SKOV3 CD117+CD44+CSCs was higher than in SKOV3 tumor tissues and non-CD117+CD44+CSCs." (PMID 25792974, 2015). "Some of lncRNAs, such as HOTAIR and MALAT-1, are proposed to promote tumor cell metastasis, but further functional tests are required." (PMID 26415221, 2015). "To assess the effect of the down-regulation of HOTAIR in CD117+CD44+-shHOTAIR on tumor metastasis, we used H&E staining to detect if there was tumor cell metastasis in the lung tissues." (PMID 25792974, 2015). "When compared between pure-SCLC tumor tissues (n = 24) and combined-SCLC tumor tissues (n = 11), HOTAIR expression was significantly higher in pure SCLC (P = 0.009)." (PMID 24591352, 2014). "The aim of the present study was to examine the expression pattern of HOTAIR in NSCLC and to evaluate its biological role and clinical significance in tumor progression." (PMID 24103700, 2013). "Therefore HOTAIR may play a functional role in tumor cell growth in PCa." (PMID 23936419, 2013). "To explore the molecular mechanisms by which HOTAIR contributes to the phenotypes of NSCLC cells, we investigated potential targets involved in tumor invasion and metastasis." (PMID 24103700, 2013). "Preclinical studies have demonstrated that silencing of MALAT1, HOTAIR, or SAMMSON using antisense oligonucleotides (ASOs) or gapmeRs dramatically reduces intratumoral vessel density and tumour growth and shows synergistic effects with BRAF/MEK inhibitors and bevacizumab." (PMID 41463281, 2025). "In addition to miRNA, several lncRNAs, including HOTAIR, MALAT1, TUG1, and NEAT1, play crucial roles in regulating gene expression and significantly impact tumor progression." (PMID 40806675, 2025).
tumor (continued). "Similarly, lncRNAs such as HOTAIR and MALAT1 are critical in chromatin remodeling and transcriptional reprogramming, promoting tumor growth and therapy resistance." (PMID 41011238, 2025). "Specifically, downregulation of transcription factors and subsequent decrease in miR-126 levels leads to increased expression of HOTAIR, EZH2, and DNMT1, thus impairing the epigenetic control of genes involved in differentiation, development, and tumor suppression." (PMID 40141248, 2025). "In addition, HOTAIR is involved in regulating key pathways such as Wnt/β-catenin and PI3K/Akt, both of which play a crucial role in tumor resistance and immune evasion." (PMID 40723840, 2025). "Furthermore, reduced expression of HOTAIR and DNMT1 led to decreased tumour volume and weight in mice injected with CML cells." (PMID 40387409, 2025). "lncRNAs such as HOTAIR and MALAT1 affect gene expression through mechanisms like chromatin remodeling and transcriptional interference, which are pivotal in processes such as metastasis and tumor growth." (PMID 40959208, 2025). "Additionally, miR-204 modulates signaling pathways like PI3K/AKT and interacts with HOTAIR and DSCAM-AS1 lncRNAs, further influencing tumor progression." (PMID 39199587, 2024). "These insights suggest that lncRNAs like HOTAIR and ANRIL might promote carcinogenesis by strategically silencing tumor suppressor genes." (PMID 38329598, 2024). "Furthermore, HOTAIR modulates the epithelial-mesenchymal transition (EMT) through the miRNA sponge mechanism, a pivotal process for tumor invasion and metastasis." (PMID 39286016, 2024). "In addition, CAFs can also initiate the expression of lnc HOTAIR to promote EMT and tumor metastasis." (PMID 37666813, 2023). "Some well-studied lncRNAs such as HOX Transcript Antisense RNA (HOTAIR), X-Inactive Specific Transcript (XIST), and Nuclear Enriched Abundant Transcript1 (NEAT1) demonstrated to participate in tumor progression, including regulating cell proliferation, cell cycle, apoptosis, and metastasis." (PMID 36816357, 2023). "For instance, Tian and colleagues demonstrated that curcumol could downregulate HOTAIR expression, which induces the suppression of EZH2, leading to the inhibition of tumor growth." (PMID 37240232, 2023). "Moreover, in the tumor tissues of mice after JMJD6 silencing, the expression of HOTAIR was restricted, while further overexpression of ERK2 (MAPK1) did not affect the expression of HOTAIR." (PMID 37880710, 2023). "Second, HOTAIR down-regulates the expression of E-cadherin and miR-217, then activates the DACH1/JAK3/STAT3 and Wnt/β-catenin pathways, which are involved in the tumor’s EMT ability, which is important for primary tumor formation and metastasis." (PMID 36924407, 2023). "Liu showed that HOTAIR recruits and binds PRC2 to inhibit miR34a by epigenetic inheritance, which controls the targets C-Met (HGF/C-Met/Snail pathway) and Snail, contributing to the EMT process in GC cells and accelerating tumor metastasis." (PMID 36672374, 2023). "In addition, after SKLB325 treatment, the expression of HOTAIR and ERK2 (MAPK1) was diminished in the tumor tissues, accompanied with slow proliferation and accelerating apoptosis of tumor cells." (PMID 37880710, 2023). "HOTAIR and the SNHG12–miR-330-5p–TNC axis might promote tumor progression via tumor cell metastasis and tumor hypoxia." (PMID 35968275, 2022). "It has been demonstrated that hypoxia could induce the aberrant expression of lncRNAs, such as H19, HOTAIR, and NEAT1 to regulate tumor biology." (PMID 35846431, 2022). "Bioinformatics analysis revealed that the expressions of HOTAIR and Suv39H1 were higher in tumor tissues than those in noncancerous tissues." (PMID 35619625, 2022).
tumor (continued). "We reviewed the literature and found that AGAP2-AS1, HOTAIR, and HOXC-AS1 (three lncRNAs of GILncSig) are not only related to the malignant progression of tumors and poor prognosis of patients but also affect the tumor immune microenvironment." (PMID 35571034, 2022). "Recently, another mechanism by which HOTAIR could contribute to the leukemogenic process was found and it involves silencing of the HOXA5 tumor-suppressor gene through increased methylation of its promoter." (PMID 36362925, 2022). "HOTAIR is required for breast CSC self-renewal and tumor propagation." (PMID 36273585, 2022). "Recently, a research group evaluating the expression of HOTAIR in 49 GC tissues and their adjacent non-tumor tissues has reported that expression level of HOTAIR is not related to the proportion of H. pylori infection (P = 0.30)." (PMID 35186192, 2022). "Finally, HOTAIR was shown to influence the autophagy and imatinib sensitivity of GIST cells in mouse tumor models." (PMID 33824300, 2021). "LncRNAs such as HOTAIR, MALAT1, ANRIL and SRA are up-regulated in tumors and play the role of oncogenes, while MEG3, GASS and LncRNA-p21 are down-regulated in tumors and play a role of tumor suppressors." (PMID 34616746, 2021). "Statistical elaboration showed that, while there is not direct relation between HOTAIR expression and GEP-NEN tumor location, a positive relationship between HOTAIR expression and grade has been detected." (PMID 34208964, 2021). "However, miR-7 is dramatically suppressed by HOTAIR through HOXD10; thus, the tumor suppressive roles of miR-7 have to be overthrown." (PMID 34073224, 2021). "Similar to our study design, HOTAIR depletion could reduce cellular motility, invasiveness and EMT in human tumor cells." (PMID 34225739, 2021). "Moreover, previous reports indicated that MUC1, COPS6, HOTAIR, COL6A1 were served as biomarkers for PAAD and had tumor-suppressive or tumor-promoting ability." (PMID 34285140, 2021). "The results of functional assays showed that knockdown of HOTAIR could inhibit the proliferation, migration, invasion and the activity of the AKT signaling pathway of BC cells in vitro, and reduce BC tumor growth in vivo." (PMID 32694942, 2020). "Previous studies have suggested that some lncRNAs may promote tumor progression through the dysregulation of tumor proliferation, apoptosis (e.g., MA-LINC1, HOTAIR), metastasis (e.g., MALAT1), and angiogenesis (e.g., MIAT, MEG3)." (PMID 32083005, 2020). "In breast cancer, HOTAIR overexpression sustains the expression levels of c-myc, Twist, and miR-9, thus conferring to CSC pool maintenance and EMT promotion, while it reduces the tumor suppressor miR-7 through positive regulation of HoxD10." (PMID 32932969, 2020). "Therefore, HOTAIR regulates methylation or demethylation of H3K4me2 at the H3K27 site, which is involved in proliferation, apoptosis, and metastasis of tumor cells." (PMID 33123473, 2020). "Propofol may exert similar inhibitory effect on in vivo tumor metastasis, and this effect was probably due to the reduced expression of STAT3, HOTAIR, and WIF‐1 expression and subsequent activation of Wnt signaling pathway." (PMID 31953926, 2020). "Furthermore, HOTAIR promotes the expression of HK2, and HOTAIR and HK2 are overexpressed in both the serum and tumor tissues of PDAC patients." (PMID 33256814, 2020). "HOTAIR may also sequester hsa-miR-613 in NSCLC tumor tissues and cell lines (H1299, H23, H292, and A549), and hsa-miR-221 in NSCLC tumor tissues and cell lines (A549, H322, and H1299)." (PMID 32438606, 2020). "In lung cancer models, HOTAIR could activate BMI1, CD44, OCT4, and CD133, whose expression is critical for tumor cell reprogramming toward a CSC phenotype." (PMID 32932969, 2020). "In NSCLC tumor tissues and A549 cell line, Caveolin 1 (CAV1) was described to upregulate HOTAIR." (PMID 32438606, 2020).